IL6 (interleukin 6)
Diseases named in the same sentence as IL6 in open-access papers (continued):
Sharing a sentence is not in itself a finding about the gene and the disease.
asthma (continued). "While IL-6 responses, overweight and child atopy/asthma were measured directly, other variables were assessed by questionnaires, which are sensitive to bias." (PMID 22685596, 2012). "We observed an increase in the level of IL-1β, IL-4, IL-5, IL-6, IL-8, and IL-10 in asthma patients as compared to the controls." (PMID 23226977, 2012). "IL-6 release has been demonstrated to be up-regulated during exacerbation periods of several respiratory diseases including asthma, cystic fibrosis and COPD." (PMID 21655222, 2011). "In further support of this, IL-6 levels have been shown to be elevated in various pulmonary disorders associated with fibrosis, including IPF, asthma and COPD." (PMID 21799929, 2011). "As an inflammatory and pro-fibrotic cytokine, IL-6 is involved in the pathogenesis of lung diseases such as asthma, COPD and idiopathic pulmonary fibrosis (IPF)." (PMID 21799929, 2011). "High levels of pro-inflammatory IL-6 and IL-17 cytokines and low levels of an anti-inflammatory cytokine IL-10 have been observed in asthmatic patients, suggesting that a functional vitamin D insufficiency/deficiency may be responsible for an increased probability of developing asthma." (PMID 21494627, 2011). "Previous studies in obese asthmatics that include a substantial number of subjects with severe asthma have shown an inverse correlation of IL-6 in induced sputum with FEV1% predicted in a cohort of asthmatics." (PMID 20205953, 2010). "This type of analysis builds from simple to multiple regression analyses to investigate the potential contribution of mediators (e.g. IL-6) to an already established relationship (e.g. asthma and impaired lung function)." (PMID 20205953, 2010). "In asthma, several reports have also shown elevated IL-6 levels in BALF and serum as well as increased IL-6 secretion from lung epithelial cells collected from asthmatics." (PMID 20205953, 2010). "For this reason, we have characterised the role of miR-146a during IL-1β-induced IL-6 and IL-8 release from primary HASM cells, which are known to contribute towards chronic inflammation associated with the development of asthma." (PMID 20525168, 2010). "In mild-moderate asthma, IL-6 dissociates from other proinflammatory biomarkers, but correlates with IL-13 levels." (PMID 20205953, 2010). "Upregulation of IL-6 is also detected within airway epithelial cells in symptomatic asthma patients." (PMID 20804555, 2010). "We anticipated that polycationic proteins, that are abundantly present in the airways of patients with asthma and that have been shown to attenuate cellular arginine uptake, would also lead to exaggerated IL-6 and IL-8 production." (PMID 19575800, 2009). "Dixon et al9 noted the positive correlation between serum interleukin (IL-6) levels and asthma severity." (PMID 20396654, 2008). "The increased expression of IL-6 in HASM cells obtained from asthma patients was due to differences in the activation pattern of several transcription factors." (PMID 16670028, 2006). "Our cytokine analysis revealed that pediatric non-T2 asthma is characterized by elevated Th1 and Th17 cytokines, including IL-2, IL-6, IFN-γ, and IL-17A, accompanied by the downregulation of immunoglobulin-associated genes, indicating an attenuated Th2 signature and reduced atopy." (PMID 41601686, 2026). "For the present study, we hypothesised that exaggerated IL‐6 release in response to repeated respiratory viral infection is central to the development of asthma exacerbations." (PMID 41099307, 2026). "Hence, IL‐6 directly and/or indirectly promoted the existing allergic inflammation, thereby worsening the pathophysiological hallmarks of experimental asthma." (PMID 41099307, 2026). "Additionally, patients with asthma carrying the epigenetic signature of a trained IL‐6 response exacerbate more frequently." (PMID 41099307, 2026).
asthma (continued). "Additionally, patients with asthma and with trained IL‐6 response, defined by hypomethylation of the IL6 gene, exacerbated more frequently, with paediatric patients showing features of a more severe disease course in the future." (PMID 41099307, 2026). "At the same time, among patients with controlled asthma, the coefficients of determination (R2) were 0.194, 0.093 and 0.152 for TNFα, IL-6 and IL-8, showing a weak dependence (r = 0.39 and r = 0.3050 for IL-6 and IL-8) and a moderate dependence (r = 0.44) for TNFα." (PMID 40361972, 2025). "Indeed, the IL-6 and IL-17 levels were increased in the high IL-36γ subgroup and positively correlated with IL-36γ in the asthma patients in our study." (PMID 40115968, 2025). "Patients with asthma and high IL-6 were more likely to be Black and showed increased CRP." (PMID 39714726, 2025). "IL-36α may play a more prominent role in airway immunopathology compared to systemic circulation, as sputum IL-36α levels were elevated and strongly correlated with IL-6 in patients with mild asthma." (PMID 40115968, 2025). "It is indeed known that excess adipose tissue leads to an overproduction of pro-inflammatory leptin, which in turn feeds the inflammatory process and is responsible for the synthesis of pro-inflammatory cytokines such as IL-6, which can at the same contribute to the pathogenesis of asthma." (PMID 40559430, 2025). "In the present study, asthma patients with high IL-36Ra and IL-38 levels showed a deteriorating asthma status and were prone to SAEs; additionally, IL-36Ra and IL-38 were positively correlated with the agonistic IL-36 cytokines IL-6, IL-13, IL-17, and IFN-γ." (PMID 40115968, 2025). "Both lung and circulating IL-6 levels are elevated in asthma." (PMID 39714726, 2025). "Additionally, SIRT1 influences pulmonary function in asthma patients through its effect on IL-6 levels via the Akt signaling pathway." (PMID 41008562, 2025). "Moreover, elevated IL-6 levels, which promote Th2 activation and allergic responses while inhibiting regulatory T cell activity, are found in the airways of patients with asthma." (PMID 40573126, 2025). "However, in the multivariable model, only Black race and CRP were positively correlated with the probability of high IL-6 asthma." (PMID 39714726, 2025). "Researchers have realized the link between IL-6 and the development of asthma." (PMID 40181938, 2025). "Both lung IL-6 and circulating IL-6 levels are up-regulated in patients with asthma." (PMID 39714726, 2025). "Multivariable analysis of FEV1 (Supplement) and FVC (Supplement) revealed negative associations with Black race, female sex, CRP, IL-6, HbA1c, metabolic dysfunction, age, and current asthma, and a positive association with height." (PMID 39714726, 2025). "IL‐6 is an important element in the pathogenesis of AR and asthma." (PMID 41179970, 2025). "Rhinoviruses infection promotes the secretion of cytokines from epithelial cells, such as IL-6, IL-8, IL-11, and GM-CSF, which may trigger the onset of asthma." (PMID 38904891, 2025). "Mast cells expressing CD40L can enhance IgE production by promoting class switching in B cells (with the involvement of IL-4, IL-13, and IL-6), which may exacerbate asthma symptoms." (PMID 41155381, 2025). "The reduction in IL-6 in humans could be a potential mechanism of action in improving asthma symptoms." (PMID 40137143, 2025). "Notably, IL-6 and IL-23 also contributed to corticosteroid resistance in asthma models characterized by neutrophil infiltration." (PMID 41196933, 2025). "IL-1β and TNF-α induce IL-6, which plays a role in inflammation, autoimmunity, cancer, and asthma." (PMID 41155381, 2025). "Our study showed that acupuncture inhibits IL-6 secretion upon in vitro antigen restimulation of lung DCs, suggesting its role in suppressing pro-inflammatory cytokine production from CD11b+ DCs and alleviating the Th2 response in asthma." (PMID 40405264, 2025).
asthma (continued). "Some studies also found that probiotics could improve lung function and clinical symptoms for asthma patients, accompanied by a decrease of cytokines such as interleukin‐6 (IL‐6), IL‐17, and IL‐21." (PMID 39479674, 2024). "Additionally, wedelolactone inhibited the IL-1α, IL-1β, IL-6 and IL-17a mRNA expression, which were related to neutrophilic predominant asthma." (PMID 38459541, 2024). "Indeed, intranasal administration of asthma-protective bacteria in a mouse model of asthma has been shown to trigger a local pro-inflammatory response in the airways, characterized by a sustained systemic increase in IL-6." (PMID 38338861, 2024). "For instance, studies have shown that PFOA can induce the activation of the NLRP3 inflammasome in human bronchial epithelial cells, which triggers the release of pro-inflammatory cytokines like interleukin- 6 (IL-6) and IL-1β, contributing to airway inflammation and asthma exacerbation​." (PMID 39677147, 2024). "It was demonstrated that obese patients with asthma had elevated levels of IL-6 in serum in comparison with overweight and nonobese subjects, and this was associated with asthma severity." (PMID 38542187, 2024). "In the context of obese asthma, pro-inflammatory cytokines, such as IL-6 and IFN-γ, or adipokines could be added to the culture media." (PMID 38474191, 2024). "Type 2-high and type 2-ultra-high asthma again involve IL-4, IL-5, and IL-13, while type 2-low asthma, due to the lack of biomarkers, is described as a type with different mechanisms of disease, including IL-1β, IL-6, or neutrophil infiltration." (PMID 38785919, 2024). "Secondly, we only investigated polymorphisms within the IL-6 gene without examining other genetic variants in asthma development." (PMID 38388670, 2024). "Together with several canonical signalling pathways, including IL-6, TGF-β, and IFN signalling in conjunction with their associated EV miRNAs, these results support the concept that obesity asthma represents a unique asthma phenotype with quite specific underlying pathomechanisms." (PMID 38255279, 2024). "Also, the same study reported that the levels of miR-21-5p in exosomes correlated positively with IgE levels and correlated negatively with plasma levels of TNF-α and IL-6 in patients with moderate–severe asthma." (PMID 38337625, 2024). "PM2.5 and NO2 may influence asthma development not only through oxidative stress leading to inflammation (eg, IL-6), but also through altered immune development, increased IgE-mediated allergic sensitization, and Th17-associated responses." (PMID 38416497, 2024). "IL-1β produced after the activation of NLRP3 inflammasome positively regulates the differentiation of Th17 cells, which promotes the secretion of IL-6 and IL-8 and induces neutrophil recruitment, which may be an important factor in the acute attack of asthma." (PMID 38117410, 2024). "In mice with ova-induced bronchial asthma, the administration of EGCG via tail vein injection demonstrates a notable amelioration of asthma symptoms, along with a reduction in lung infiltration of inflammatory cells and levels of inflammatory factors IL-2, IL-6, and TNF-α." (PMID 39411430, 2024). "These immunological markers may correspond to pathophysiological characteristics of asthma: periostin, IgE, IL-5, and IL-33 for T2 asthma; IL-6, IL-8, IL-17A, and IL-33 for non-T2 asthma." (PMID 38256660, 2024). "Subsequently, Hematoxylin and eosin (H&E) staining, Masson’s trichrome (Masson) staining, Periodic acid-Schiff (PAS) staining and inflammatory cytokines assay of interleukin (IL)-4, IL-6, IL-17 were implemented to evaluate the protective effects of Chelidonium majus on asthma." (PMID 38671520, 2024). "Dietary antioxidants might inhibit NF-κB pathway, reduce cytokines as IL-6, IL-8 and T-helper 2 (crucial in asthma pathogenesis)." (PMID 39474310, 2024).
asthma (continued). "The gene signature was then used as a potential approach to understand the significance of IL-6 signaling in human asthma, reasoning that high expression of this gene signature may reflect local epithelial IL-6 activation." (PMID 38062491, 2023). "Moreover, we generated a gene signature to predict the presence of active IL-6 + sIL-6Rα signaling in asthma patients and showed this to be enriched in asthma patients with low eosinophil counts." (PMID 38062491, 2023). "The last decade or so has seen an increasing number of studies shedding light on IL-6 as key cell signaling mode in asthma-related pathways and may play a role as a biomarker of asthma." (PMID 37173781, 2023). "Higher concentrations of the pleiotropic cytokine IL-6 and the glial marker S100B were associated with more salubrious white matter metrics in asthma, but not in controls." (PMID 37377978, 2023). "In addition, Asthma is treated with inhaled corticosteroids which shut down the expression of asthma-related cytokines such as IL-6." (PMID 37173781, 2023). "The objective of this study was to assess the validity of serum IL-6 test for diagnosis of asthma." (PMID 37173781, 2023). "There is mounting evidence implicating IL-6 signaling in the pathogenesis of asthma." (PMID 37631100, 2023). "The proinflammatory cytokine IL-6, produced in adipocytes and adipose tissue macrophages, has been associated with obese T2-low asthma but not with obese atopic asthma." (PMID 37761964, 2023). "Based on these observations, we hypothesized that the therapeutic effect of QXD in asthma treatment may involve the regulation of PA content and function, potentially achieved through the modulation of macrophage IL-6 expression." (PMID 38155957, 2023). "In addition, a subgroup analysis of asthma disease status showed that IL-6 levels were increased in stable (SMD 0.69, 95% CI 0.28–1.09, P = 0.009) and exacerbation asthma (SMD 2.15, 95% CI 1.79–2.52, P < 0.00001) patients." (PMID 37173781, 2023). "Researchers have recognized a correlation between IL-6 and asthma development." (PMID 37260450, 2023). "Notably, IL-13 and IL-6 have been widely recognized for their significant involvement in asthma pathogenesis." (PMID 38078005, 2023). "Previous studies indicated a pleiotropic role for IL-6 signaling in asthma." (PMID 38062491, 2023). "Additionally, IL-6 participates in the early and late phases of the asthma response and is correlated with the severity of the condition." (PMID 37251328, 2023). "The increase of serum IL-6 in obese asthma patients was related to the impairment of lung function." (PMID 37492220, 2023). "Pharmacotherapy (inhalation of corticosteroids plus long-acting beta agonist according to the global initiative for asthma (GINA) guidelines) prescribed to a subgroup (n = 8) of the asthmatic patients with severe asthma for 12 weeks decreased IL-6 and AGE, and increased DJ-1." (PMID 37371535, 2023). "IL‐6 was associated with overweight/obese non‐allergic asthma, but not lean asthma or overweight/obese allergic asthma." (PMID 36973952, 2023). "Similarly, the consistent and widespread relationship between CSF IL-6 and dMRI indicators of better brain health in those with asthma was surprising." (PMID 37377978, 2023). "Patients with asthma have been reported to have elevated blood levels of IL-6." (PMID 36981614, 2023). "Our results suggest that a specific subgroup of IL-6 + sIL-6Rα high asthma patients exists." (PMID 38062491, 2023). "In our model, we also observed the production of epithelial-derived innate cytokines, that in addition to Th2 cytokines, make a great contribution to the inflammatory response in asthma, such as IL-1β, IL-6, and TNF-α, the latter being considered a marker of neutrophilic asthma." (PMID 36980265, 2023). "The present study was conducted to investigate the potential role of IL-6 in asthma patients." (PMID 37173781, 2023).
asthma (continued). "We sought to study the role of sIL-6Rα amplified IL-6 signaling in airway epithelium and to develop an IL-6+ sIL-6Rα gene signature that may be used to select asthma patients who potentially respond to anti-IL-6 therapy." (PMID 38062491, 2023). "More specifically, IL-6 and IL-33, two pro-inflammatory cytokines produced by airway epithelia known to play key roles in severity of asthma inflammation, were modestly yet significantly upregulated in HDM-exposed mice following Miro1 deletion in club cells when compared to Ctrl HDM-challenged mice." (PMID 37377691, 2023). "In addition, EGR3 was reported to be overexpressed in the lung of asthma patients and regulates the expression of IL-2, IL-6, and IL-8." (PMID 36979655, 2023). "There is growing evidence that IL-6 may also play an important role in the initial development and subsequent progression of asthma." (PMID 37173781, 2023). "Neutrophilic inflammation may also be associated with YKL-40 in serum and in lung tissue, as it is secreted by neutrophils, and correlates with increased severity of asthma, and with cytokines such as IL-1β and IL-6." (PMID 40980110, 2023). "As well, this circumstance also has been described in asthma patients, where some interleukins have been found raised, such as IL6, IL-4, IL-5, and IL-13, secreted from CD4+ lymphocytes, promoting an allergic inflammation which involves a worse prognosis of asthma disease." (PMID 37920579, 2023). "Increased IL-6 levels have been observed in the serum, induced sputum, and BALF of asthma patients and are associated with compromised lung function and asthma severity." (PMID 37631100, 2023). "IL-6 can induce Th17 differentiation, and blocking IL-6 may be a potential target for the treatment of asthma." (PMID 37377958, 2023). "Little is known regarding the influence of these obesity-related inflammatory pathways on the efficacy of asthma biologics and whether measurement of serum IL-6, IL-17 or adiponectin levels may predict response to biologic therapies in patients with asthma." (PMID 38259298, 2023). "Upregulation of Hsa_circ_0005519 could inhibit the expression of has-let-7a-5p in CD4 T cells of asthmatic patients and promote the production of IL-13 and IL-6, thereby exacerbating asthma." (PMID 35586697, 2022). "In vitro, miR874, which may be associated with the development of asthma, has been shown to inhibit TNF-α-induced IL-6, IL-8, collagen I, and collagen III production in ASM cells." (PMID 35626330, 2022). "Particularly, expression of leptin and IL-6 appears to be increased in VAT of obese subjects with asthma, thus suggesting that these mediators could promote airway inflammation." (PMID 35806353, 2022). "In conclusion, Danlong Dingchuan Decoction may act on IL-4, IL-6, IL-8, and other Th2 cytokines and reduce the expression of Th2 cytokines with a variety of active compounds in treating asthma." (PMID 35186104, 2022). "These cytokines are well-known regulators of Th2-mediated eosinophilia; therefore IL-6 inhibition may enhance type 2 response in asthma." (PMID 35408882, 2022). "Whether the effect of IL6R on asthma arise from the modulatory role of IL6 on the immune response or a more direct effect of for example, sIL‐6R on CD4 T cells or airway epithelial cells is still unresolved." (PMID 36434743, 2022). "Experimental evidence indicates that IL-6/sIL-6R trans-signaling might play an essential role in the development of asthma and dermatitis." (PMID 35493452, 2022). "Interestingly, it has been reported that epithelial cells isolated from asthma patients produce more IL-6 than healthy individuals." (PMID 36032502, 2022). "In asthma, the novel function of IL-6 is the control of Th1/Th2 differentiation." (PMID 35743888, 2022). "Recent advances in our understanding of asthma pathogenesis suggest that both IL-6 and TNF may represent potential targets for treatment of severe neutrophilic asthma." (PMID 35408882, 2022).